SPEG (striated muscle enriched protein kinase)
Diseases named in the same sentence as SPEG in open-access papers (continued):
Sharing a sentence is not in itself a finding about the gene and the disease.
Diabetes (1 paper, 2017). "Among underlying conditions and risk factors, speH, speJ, and speK were significantly associated with chronic skin lesions, and speG was significantly associated with diabetes." (PMID 28719668, 2017).
Hypertension (1 paper, 2022). The presence of chronic increased pressure in the systemic arterial system. "As rs12474050 was reported as a cis-eQTL of SPEG by the previously published hypertension GWAS, in which the GTEx database V7 was used to annotate these cis-eQTLs, we further evaluated its association with SPEG expression across 49 tissues in GTEx database V8." (PMID 36685827, 2022).
malignant pleural mesothelioma (1 paper, 2025). A malignant neoplasm that arises from mesothelial cells in the pleura and shows a diffuse growth pattern. "In a kinome, CRISPR‐Cas9 knockout screen in which kinases in malignant pleural mesothelioma (MPM) cancer cells were targeted WEE1, AURKA, MPP3, MAP3K12, DGKD and SPEG could be identified as candidate genes." (PMID 40242936, 2025).
Obesity (1 paper, 2022). Accumulation of substantial excess body fat. "Patients with neurodegenerative diseases had significantly lower levels of SPEG methylation, which is strongly associated with obesity." (PMID 36733447, 2022).
oropharyngeal cancer (1 paper, 2020). Carcinoma, predominantly squamous cell, arising from the epithelial cells of the oropharynx. "Part of the effect of smoking on survival in those with oropharyngeal cancer may be mediated by methylation at the SPEG gene locus." (PMID 32600451, 2020).
pneumonia (1 paper, 2016). An acute, acute and chronic, or chronic inflammation focally or diffusely affecting the lung parenchyma, caused by an infection in one or both of the lungs (by bacteria, viruses, fungi, or mycoplasma.). "However, a role for speG in virulence of MRSA and pathophysiology of pneumonia has not yet been established." (PMID 27249225, 2016).
prostate carcinoma (1 paper, 2025). A carcinoma that arises from epithelial cells of the prostate gland. "Current research on SPEG, ASPSCR1, and CEP89 in prostate cancer is relatively limited." (PMID 40297177, 2025).
sarcoma (1 paper, 2013). A usually aggressive malignant neoplasm of the soft tissue or bone. "In the whole sarcoma collection, SPEG was hypomethylated and highly expressed exclusively in LMS samples." (PMID 24345474, 2013). "The top markers for differentiation of sarcoma cluster 2 (LMS samples) and sarcoma cluster 5 (MLS samples) were SPEG (striated muscle preferentially expressed protein kinase) and NNAT (neuronatin), respectively." (PMID 24345474, 2013).
thromboembolic disease (1 paper, 2021). "The identified risk factors on chromosomes 2, 6, 7, 8, 10, 16, and 17 contain genetic variants and genes related to cilia dysfunctions (DNAH7 and CLUAP1), cardiovascular diseases (DES and SPEG), thromboembolic disease (STXBP5), mitochondrial dysfunctions (TOMM7), and innate immune system (WSB1)." (PMID 33536081, 2021).
type 2 diabetes (1 paper, 2023). "For comparison, CpGs that were likely to be secondary to the effects of type 2 diabetes (in PBX1, SPEG, MIR657 and RBFOX1) based on the results of the 2SMR analysis were enriched for perinatal and neurological traits in addition to cardiometabolic and anthropometric traits." (PMID 37202507, 2023).
infection (8 papers, 2011 to 2024). The state of being infected such as from the introduction of a foreign agent such as serum, vaccine, antigenic substance or organism. "SpeA, speK, and speG are associated with GAS virulence; however, it is unclear if they are markers of invasive infection." (PMID 39055978, 2024). "We only observed that the significant up-regulation of SPEG upon SARS-CoV-2 infection with high multiplicity of infection equal to 0.1 in cardiomyocytes." (PMID 36685827, 2022). "The potassium transporter gene KCTD11 of the in vitro M cells was markedly upregulated after ΔspeG infection, indicating that speG plays a role in suppressing the expression of this potassium transporter of M cells during S. Typhimurium infection." (PMID 27064787, 2016). "The expression of speG in S. Typhimurium was downregulated in some of the 22 in vitro infection-relevant environmental conditions, particularly late stationary phase and pH3 shock." (PMID 27064787, 2016). "On the other hand, the outcome of intracellular macrophage survival assays, performed in mouse peritoneal macrophages, and of a competitive-infection assay on J774 macrophage cell culture, shows a decrease of survival properties in the speG-complemented Shigella strains." (PMID 22102881, 2011). "As SARS-CoV-2 infection could damage the cardiac tissue both directly and indirectly, the upregulation of SPEG, partially increased in higher magnitude in female cardiomyocytes, would be a potentially compensatory response and self-cardioprotective action due to the infection of SARS-CoV-2 in heart." (PMID 36685827, 2022). "To test this hypothesis, we quantified H2AX phosphorylation in response to DNA damages after HeLa cell infection by E. coli SP15 and deletion mutants of speE and speG genes." (PMID 31578245, 2019).
myopathy (6 papers, 2020 to 2024). A disease of the muscle in which the muscle fibers do not function properly. "Indeed, myopathies in patients with nonsense and frameshift mutations found in obscurin or SPEG lend additional credence to this finding and suggest a high degree of functional evolutionary conservation." (PMID 33801198, 2021). "Reducing DNM2 could increase the life span, body weight, and motor performance of SPEG-deficient mice, thereby rescuing SPEG-related myopathy, but not alleviate the cardiac dysfunction." (PMID 35763354, 2022).
cancer (3 papers, 2019 to 2025). A tumor composed of atypical neoplastic, often pleomorphic cells that invade other tissues. "Mutations in SWI/SNF and chromatin-remodeling complex (SMARCA4, COL6A3, RYR2, and SPEG) contributed to cancer and neurological disorders." (PMID 31428092, 2019).
neuromuscular disease (3 papers, 2015 to 2024). "Mutations were found in eight previously known neuromuscular disease genes (CHRND, CHNRG, ECEL1, GBE1, MTM1, MYH3, NEB and RYR1) and four novel neuromuscular disease genes (GPR126, KLHL40, KLHL41 and SPEG)." (PMID 26933539, 2015). "Four novel genes related to neuromuscular diseases were found, consisting of GPR126, KLHL40, KLHL41, and SPEG genes." (PMID 37989827, 2024). "Within this cohort, mutations were found in eight previously known neuromuscular disease genes (CHRND, CHNRG, ECEL1, GBE1, MTM1, MYH3, NEB and RYR1) and four novel neuromuscular disease genes were identified and have been published as separate reports (GPR126, KLHL40, KLHL41 and SPEG)." (PMID 26578207, 2015).
neurodegenerative disease (1 paper, 2022). A disorder of the central nervous system characterized by gradual and progressive loss of neural tissue and neurologic function. "By targeting the SPEG protein in the hippocampus, acetamidobenzoic acid, a metabolite associated with high-fiber diet, may improve diabetic and neurodegenerative diseases in obese people." (PMID 36733447, 2022). "Therefore, acetaminobenzoic acid may target SPEG in the hippocampus, thereby affecting the autophagic balance of the hippocampus and regulating the hippocampal-hypothalamic endocrine axis, improving diabetic and neurodegenerative disease states." (PMID 36733447, 2022).
SPEG also shares sentences with these, for which no sentence is quoted: Skeletal myopathy (3 papers); cardiovascular diseases (2); adenocarcinoma of the (1); cardiac diseases (1); cardiac hypertrophy (1); coronary artery disease (1); genetic disease (1); hypertrophic obstructive cardiomyopathy (1); muscle disorders (1); neurological disorders (1); neuropathy (1); ophthalmoplegia (1); Parkinson disease (1); peripheral arterial disease (1); Respiratory distress (1); respiratory impairment (1); scarlet fever (1); scoliosis (1); skin infection (1).